MIR3191 (microRNA 3191)
Synonyms: hsa-mir-3191; mir-3191
Gene: MicroRNA gene on chromosome 19 (47,226,944 to 47,227,019, reverse strand). Ensembl gene ENSG00000284411.
Diseases named in the same sentence as MIR3191 in open-access papers:
MIR3191 is named in the same sentence as 1 disease in open-access papers, as found by Europe PMC text mining. Sharing a sentence is not in itself a finding about the gene and the disease.
MIR3191 shares sentences with these, for which no sentence is quoted: tumours (1 paper).